TPCN2 (two pore segment channel 2)
Diseases named in the same sentence as TPCN2 in open-access papers:
TPCN2 is named in the same sentence as 56 diseases in open-access papers, as found by Europe PMC text mining. Sharing a sentence is not in itself a finding about the gene and the disease. The quoted sentences say what the papers report.
melanoma (19 papers, 2011 to 2025). A malignant, usually aggressive tumor composed of atypical, neoplastic melanocytes. "Though they transport different molecules, these SNPs in SLC45A2 and near TPCN2 both demonstrated associations with melanoma that were larger in males than in females." (PMID 25789475, 2015). "In our study, a second SNP in this region (rs7117034, ~117kb downstream of TPCN2) was also marginally associated with melanoma risk overall (p = 3.7x10-4)." (PMID 25789475, 2015). "We also observed a marginally significant association with melanoma in TPCN2, suggesting a potential male-specific pleiotropic association with both melanoma and prostate cancer." (PMID 25789475, 2015). "Additionally, we were able to provide some evidence of an association with melanoma for one SNP near solute-carrier gene TPCN2 that showed potential differences in effect by sex, with a larger effect in males than females." (PMID 25789475, 2015). "Many pigmentation genes linked to melanoma in recent GWAS such as TPCN2, ASIP, KIT, NCKX5, TYR, IRF 4, OCA2 and TYRP1 have been linked to melanoma and some of them like MC1R have dual roles in pigmentation and immune responses but many other functions of these genes remain to be discovered." (PMID 23796690, 2013). "Further, knockout of the TPCN2 gene in murine primary melanoma cells decreased initial proliferation rates by slowing G2 phase progression." (PMID 36046356, 2022). "In summary, we provided confirmatory evidence of pleiotropic associations with melanoma for two SNPs in TERT-CLPTM1L and identified a potentially novel sex-specific association for a SNP near TPCN2/MYEOV." (PMID 25789475, 2015). "Recent GWAS have unveiled association between SNPs or genetic variants in MC1R, TPCN2, ASIP, KITLG, SLC24A5, TYR, IRF4, OCA2/HERC2, SLC24A4, SLC45A2, TYRP1, and pigmentation as well as melanoma." (PMID 21559390, 2011). "Genotype GA in rs72932540 (in close proximity to the TPCN2 gene) showed higher odds of malignant melanoma (MM) (OR: 1.15, 95% CI: 1.042–1.26, P value = 0.00512** vs. A/A), whereas genotype GA in rs3750965 in TPCN2 showed lower odds of MM (OR: 0.91, 95% CI: 0.84–0.99, P value = 0.02334* vs. A/A)." (PMID 34253731, 2021). "This SNP is located near TPCN2, an ion transport gene containing SNPs which have been previously associated with hair pigmentation but not melanoma risk." (PMID 25789475, 2015). "Association between SNPs in the TPCN2/MYEOV region and melanoma." (PMID 25789475, 2015). "As such, variants in other ion transport genes similar to TPCN2 and SLC45A2 might also be expected to impact pigmentation and melanoma risk." (PMID 25789475, 2015). "Similarly to other ion transport genes associated with melanoma, such as SLC45A2, variants in TPCN2 may impact melanogenesis through pH regulation." (PMID 25789475, 2015). "We first used CRISPR/Cas9 genome editing to knockout (KO) the TPCN2 gene in CHL1 and B16-F0 (murine primary melanoma) cell lines." (PMID 32846966, 2020).
Parkinson disease (8 papers, 2015 to 2025). A progressive degenerative disorder of the central nervous system characterized by loss of dopamine producing neurons in the substantia nigra and the presence of Lewy bodies in the substantia nigra and locus coeruleus. "Interestingly, a recent transcriptomic meta-analysis of blood samples from sporadic Parkinson's patients found that TPCN2 was one of the top 20 genes with altered expression." (PMID 29746898, 2018).
type 2 diabetes (6 papers, 2016 to 2024). "TPCN2 plays a role in metabolic regulation, and the rs1551305 single nucleotide polymorphism is associated with type 2 diabetes risk." (PMID 26918892, 2016). "We selected 6 SNPs in the TPCN2 gene cluster and examined their status as risk factors for developing type 2 diabetes." (PMID 26918892, 2016). "This might be the main reason for the association between the genetic variation of TPCN2 and the risk of type 2 diabetes." (PMID 26918892, 2016). "The aim of this study was to determine whether TPCN2 genetic variants are associated with type 2 diabetes and to elucidate which variants in TPCN2 confer diabetes susceptibility in the Chinese population." (PMID 26918892, 2016). "This suggests that the genetic variation of rs1551305 in TPCN2 might be associated with insulin; however, the precise role of TPCN2 with regard to type 2 diabetes risk is still under investigation." (PMID 26918892, 2016). "While we found no SNP association studies for PIKfyve, certain variants of the TPCN2 gene coding for cation-selective ion channel were found to be associated with type 2 diabetes mellitus (T2DM) and hair color." (PMID 33763088, 2021). "In our study examining the relationship between the genetic variation of rs1551305 in TPCN2 and risk of type 2 diabetes, subjects who harbored the AA genotype of the TPCN2 rs1551305 SNP had a higher incidence of type 2 diabetes." (PMID 26918892, 2016). "The purpose of our study was to determine whether the TPCN2 genetic variation is related to type 2 diabetes." (PMID 26918892, 2016).
albinism (5 papers, 2021 to 2025). A congenital disorder characterized by partial or complete absence of melanin pigment in the eyes, hair, or skin. "The TPCN2 gene has been recently implicated (2023) as a novel disease-causing gene in the newly discovered dominant type of albinism." (PMID 38279271, 2024). "Here we identify a de novo point mutation, p.R210C, in the TPCN2 gene which encodes Two Pore Channel 2 (TPC2) from a patient with albinism." (PMID 36641477, 2023). "This extends the phenotype of patients with TPCN2 variants, warranting further investigations in patients with alterations of this gene, and raises the question whether TPCN2 might be considered as an albinism gene." (PMID 39809949, 2025). "Considering the wide phenotypic spectrum of albinism, it is possible that TPCN2 will become a new albinism gene, opening a new chapter of “patients with generalized hypopigmentation but no or little ocular features”." (PMID 39809949, 2025). "We have performed an analysis of the common TPCN2 variants—some of which have already been implicated as modifiers of pigmentation —in the WES analyzed Hungarian albinism cohort (n = 6) and in controls (n = 87)." (PMID 38279271, 2024). "Our segregational analysis and in vitro functional experiments suggest that the detected novel rare TPCN2 variant alone is not a disease-causing variant in albinism." (PMID 38279271, 2024). "However, key evidence is still lacking for the TPCN2 gene to be accepted as a causative gene for albinism." (PMID 36641477, 2023).
bladder cancer (4 papers, 2017 to 2021). "The fact that TPCN2 is induced by nicotinic acid raises questions about potentially novel mechanisms that may underlie well-established link between bladder cancer and smoking." (PMID 28589857, 2017). "In contrast to previous findings that had identified TPC2 overexpression as a potential risk factor for skin cancer, TPCN2 expression was found to be significantly associated with increased survival in bladder cancer (P-value = 3.56E–02)." (PMID 31867325, 2019).
breast carcinoma (3 papers, 2019 to 2022). "Carriage of TPCN2 rs35264875:TA or rs72932540:GA or P2RX4 rs28360472:GA was associated with a higher general risk of developing breast cancer (OR: 1.06, 95% CI: 1.02–1.1, P = 0.006**, OR: 1.1, 95% CI: 1.05–1.16, P = 7.2e−05***, OR: 1.1, 95% CI: 1–1.22, P = 0.0478*, respectively, vs. A/A)." (PMID 34253731, 2021).
COVID-19 (3 papers, 2020 to 2024). A disease caused by infection with severe acute respiratory syndrome coronavirus 2. "Our findings suggested that targeting NRP1 or TPCN2 with chemicals was a potential therapeutic strategy for COVID-19." (PMID 36314791, 2022).
diabetes (3 papers, 2016 to 2021). "Furthermore, both the rodent Tpcn2 and the orthologous human TPCN2 gene have been identified as potential causal genes for diabetes-associated traits." (PMID 26769314, 2016). "Therefore, it is possible that variants within TPCN2 may be associated with diabetes in humans." (PMID 26918892, 2016). "The lack of an association between TPCN2 polymorphisms and BMI in diabetes patients in this study might be due to the presence of very little brown adipose tissue in adults." (PMID 26918892, 2016).
oral squamous cell carcinoma (3 papers, 2010 to 2022). "A similar correlation has been reported for cell lines from oral squamous cell carcinoma (TPCN2, CCND1, ORAOV1, ANO1, FADD, PPFIA1 and EMS1; FADD, PPFIA1 and EMS1)." (PMID 20664600, 2010).
lysosomal storage disease (2 papers, 2022 to 2024). A metabolic disorder caused by mutations in proteins critical for lysosomal function, including lysosomal enzymes, lysosomal integral membrane proteins, and proteins involved in the post-translational modification and trafficking of lysosomal proteins. "Perinuclear lysosome redistribution was seen in cells overexpressing TRPML1-L106P (a mutant associated with mucolipidosis type IV, an autosomal recessive lysosomal storage disorder), TPCN1, and TPCN2, but not with wild-type TRPML1, when treated with P4." (PMID 38295116, 2024).
metastatic cancer (2 papers, 2020 to 2021). A carcinoma which has spread from the original site of growth to another anatomic site. "In summary, our study found a novel association between genetic variants in TPCN2 and P2RX4 and the risk of developing cancer, metastatic cancer, cancer recurrence at a global level, or various types of cancer at the local level in the UK Biobank population." (PMID 34253731, 2021).
Obesity (2 papers, 2021 to 2025). Accumulation of substantial excess body fat. "For instance, a study conducted on male mice found that knockout of TPCN1 and TPCN2 leads to obesity in adulthood due to impaired lipid availability for thermogenesis in brown adipose tissue." (PMID 41465472, 2025).
prostate carcinoma (2 papers, 2015 to 2021). A carcinoma that arises from epithelial cells of the prostate gland. "There is a growing body of literature that recognises the importance of TPCN2 in prostate cancer." (PMID 34253731, 2021).
asthma (1 paper, 2024). "SNPs located near genes, EEFSEC and TPCN2, were found to be associated with increased risk of asthma, autoimmune and inflammatory diseases." (PMID 38659038, 2024).
colorectal cancer (1 paper, 2025). A primary or metastatic malignant neoplasm that affects the colon or rectum. "Taking a broader chromosome view shows that the two-pore segment channel 2 (TPCN2) gene had an H3K4me3 peak in the normal colon and colorectal cancer cell lines, whereas an H3K4me3 peak for the MYEOV gene was only observed in the colorectal cancer cell lines." (PMID 40141189, 2025).
Glucose intolerance (1 paper, 2016). Glucose intolerance (GI) can be defined as dysglycemia that comprises both prediabetes and diabetes. "Another study demonstrated that TPCN2 was differentially expressed in heterogeneous stock rats with glucose intolerance relative to those with normal glucose regulation and demonstrated that TPCN2 expression levels negatively correlated with fasting glucose." (PMID 26918892, 2016).
heart failure (1 paper, 2012). Inability of the heart to pump blood at an adequate rate to meet tissue metabolic requirements. "TPCN2, moreover, had similar levels of significance in all HF groups that we analysed, regardless of CM, therefore suggesting for the first time that TPCN2 up-regulation could also be involved in a general mechanism underlying heart failure, at least with ICM and DCM aetiology." (PMID 22701570, 2012).
rectal cancer (1 paper, 2021). A primary or metastatic malignant neoplasm that affects the rectum. "Carriage of TPCN2 rs35264875:TT or rs72932540:GA was associated with a higher risk of developing malignant neoplasm of the rectum (OR: 1.37, 95% CI: 1.02–1.84, P = 0.034*, OR: 1.15, 95% CI: 1.004–1.32, P = 0.044*, respectively, vs. A/A)." (PMID 34253731, 2021).
skin cutaneous melanoma (1 paper, 2020). "To evaluate the prognostic role of TPC2 (gene name TPCN2) in skin cutaneous melanoma (SKCM), we analysed TPCN2 mRNA expression levels in the Cancer Genome Atlas (TCGA)." (PMID 32846966, 2020).
cancer (23 papers, 2015 to 2025). A tumor composed of atypical neoplastic, often pleomorphic cells that invade other tissues. "We speculate that there exists an association of this genetic variant with a decreased risk of cancer at a global level, and MM and MS at a local level, due to a decrease in TPCN2 expression that has been shown to be functionally expressed in different types of cancer, using the Human Protein Atlas." (PMID 34253731, 2021). "We found that the carrying of TPCN2 rs35264875:TA was associated with an increased risk of cancer susceptibility (OR: 1.03, 95% CI: 1.01–1.05, P = 0.00138**, vs. A/A) and a decreased risk of cancer metastasis (OR: 0.74, 95% CI: 0.57–0.96, P value = 0.025* vs. A/A)." (PMID 34253731, 2021). "It would then be interesting to develop in vitro and in vivo models to examine the role of these TPCN2 mutations during tumor formation (involving neoangiogenesis) and cancer-cell migration as well as their clinical utility as diagnostic or prognostic biomarkers in different cancers." (PMID 31867325, 2019). "The recently identified TPC2 (also known as TPCN2) Ca2+-channel provides the seemingly perfect anti-cancer target." (PMID 36046356, 2022). "For the first time, we report novel associations between genetic variants of TPCN2 and P2RX4 and cancer/cancer subtypes in the UK Biobank’s population." (PMID 34253731, 2021). "Here we discovered a novel association between polymorphisms in TPCN2 and P2RX4 in cancer at the global level for subtypes of cancer." (PMID 34253731, 2021). "In this study, we leveraged a large, single resource, the UK Biobank, to explore for the first time the relationship between genetic variants of two endolysosomal proteins, TPCN2 and P2RX4, and human cancer." (PMID 34253731, 2021). "TPCN2 and P2RX4—and cancer in terms of the definition of tumour types, susceptibility, and prognosis." (PMID 34253731, 2021). "The chromosomal region harbouring TPCN2 (11q13.2) is often amplified in cancer and also contains the cyclin gene which is an established driver of oncogenesis." (PMID 29746898, 2018). "TPCN2 acts on autophagy progression and extracellular vesicle transport in cancer cells." (PMID 36140838, 2022). "TPCN2, two-pore segment channel 2, is a generally expressed, lysosome-targeting ion channel contributing to the termination of autophagy, which can affect autophagy progression and extracellular vesicle (EV) trafficking in cancer cells." (PMID 35047401, 2021). "The previously unknown risk loci are implicated in cancer development and progression (e.g. CDKL1), pigmentation (e.g. TPCN2), cardiometabolic (e.g. FADS2), and immune-regulatory pathways for innate immunity (e.g. IFIH1), and HIV-1 viral load modulation (e.g. CCR5)." (PMID 36496446, 2022). "The 11q13.3 region includes rs12275055, which maps to active enhancers and is also an eQTL for TPCN2, a gene involved in controlling the angiogenic response to VEGF and extracellular vesicle trafficking in cancer cells." (PMID 32887889, 2020). "Five of the pan-cancer ALFRED genes (BRCA1, ATM, BRCA2, NSD1, and TPCN2) were individually significantly enriched for RDGVs in cases versus controls (P < 0.05 by pan-cancer case-control analysis) with one additional gene, NIPAL3, marginally significant (P = 0.07 by case-control analysis)." (PMID 29973584, 2018). "Tpcn2 is a lysosomal non-selective Na+/Ca2+ channel, Tpcn2 suppresses the fusion between autophagosome and lysosome, leading to the accumulation of autophagosomes in cancer cells." (PMID 36006403, 2022).
tumor (10 papers, 2013 to 2025). "We observed a significant correlation between the expression and tumor grade in at least one validation cohort for each gene, except for TPCN2." (PMID 24053408, 2013). "This genetic variation at close proximity to TPCN2 might influence the expression levels of TPC2 and thereby tumour development." (PMID 34253731, 2021).
infection (5 papers, 2017 to 2023). The state of being infected such as from the introduction of a foreign agent such as serum, vaccine, antigenic substance or organism. "Infection is further positively modulated by the two-pore segment channel 2 (TPC2) protein that regulates membrane trafficking and endocytosis." (PMID 36314791, 2022). "The knockdown of TPCN2 also inhibits Ebola virus infection by blocking the endocytosis required for infection." (PMID 36314791, 2022). "Using siRNAs to knock down the expression of these individual receptors, we find that NRP1 and TPCN2 are required for SARS-CoV-2 entry into and productive infection of astrocytes." (PMID 36314791, 2022).
TPCN2 also shares sentences with these, for which no sentence is quoted: neurodegenerative disease (5 papers); cardiac hypertrophy (4); Alzheimer disease (3); Arrhythmia (3); hepatocellular carcinoma (3); age-related macular degeneration (2); cervical cancer (2); Ebola (2); metastatic melanoma (2); metastatic tumor (2); mucolipidosis type IV (2); Parkinson (2); Stroke (2); amelanotic melanoma (1); apical periodontitis (1); autoimmune disease (1); Batten disease (1); cardiac arrhythmias (1); cerebral infarction (1); colon cancer (1); lung adenocarcinoma (1); malignant neoplasms of the lip (1); neurodevelopmental disorder (1); non-alcoholic steatohepatitis (1); pharynx cancer (1); pulpitis (1); rectum adenocarcinoma (1); skin cancer (1); systemic lupus erythematosus (1); tauopathies (1).
A further 4 diseases each share a sentence with TPCN2 in 1 paper.